GOT1 (glutamic-oxaloacetic transaminase 1)
Diseases named in the same sentence as GOT1 in open-access papers (continued):
Sharing a sentence is not in itself a finding about the gene and the disease.
small cell lung carcinoma (4 papers, 2017 to 2024). Small cell lung cancer (SCLC) is a highly aggressive malignant neoplasm, accounting for 10-15% of lung cancer cases, characterized byrapid growth, and early metastasis. "Previous studies have illustrated the different uptake and retention profiles of 177Lu-octreotate and 177Lu-octreotide and their different therapeutic effects in mice with human small-cell lung cancer and/or the GOT1 NET." (PMID 38826727, 2024). "The animal models in these studies were nude mice bearing human small-intestine NET (GOT1) or human small-cell lung cancer (NCI–H69) tumors." (PMID 38826727, 2024). "Radiation-induced upregulation of SSTRs was shown in vitro in human small-cell lung cancer and in vivo in the GOT1 animal model." (PMID 35008397, 2022).
asthma (3 papers, 2019 to 2024). "By adopting a GOT1 inhibitor, they alleviated pulmonary inflammation in a mouse asthma model successfully." (PMID 33842477, 2021).
lung adenocarcinoma (3 papers, 2018 to 2023). A carcinoma that arises from the lung and is characterized by the presence of malignant glandular epithelial cells. "The GOT1 mRNA level analyzed in 56 primary lung adenocarcinoma samples was significantly higher than that in normal control tissue." (PMID 29751795, 2018). "The relevance of GOT1 as a potential target in cancer therapy was supported by a lung adenocarcinoma RNA-seq data set as well as the GEO:GSE database of metastatic melanoma where GOT1 expression was increased." (PMID 29751795, 2018). "Both MDH1/2 and GOT1/2 are highly expressed in the malate-aspartic acid shuttle pathway of lung adenocarcinoma, and the high expression of GOT2 may promote the occurrence and malignant progression of lung adenocarcinoma." (PMID 37065159, 2023).
non-small cell lung carcinoma (3 papers, 2016 to 2021). A group of at least three distinct histological types of lung cancer, including non-small cell squamous cell carcinoma, adenocarcinoma, and large cell carcinoma. "Consistent with the data from our tissue data set, we found that GOT1 expression levels were up-regulated in another Non-small cell lung carcinoma data set." (PMID 29751795, 2018). "In non-small cell lung cancer, KRAS has a profound influence on glutamine metabolism through regulation of ME1 and GOT1, the high expression of which has been shown to correlate with poorer prognosis after radiotherapy." (PMID 27924922, 2016).
osteosarcoma (3 papers, 2018 to 2023). A usually aggressive malignant bone-forming mesenchymal neoplasm, predominantly affecting adolescents and young adults. "A deletion was introduced into exon 1 of GOT1 in the 143B osteosarcoma cell line, which led to a reading frame-shift mutation." (PMID 29751795, 2018). "Moreover, GOT1-null 143B osteosarcoma cells showed accumulation of NADH and decreased NADH/NAD+ ratios when exposed to nutrient depletion." (PMID 29751795, 2018).
pancreatic adenocarcinoma (3 papers, 2018 to 2025). "In cancer, particularly in KRAS-dependent pancreatic adenocarcinoma, the Glutamate Oxaloacetate Transaminase 1 (GOT1)-MDH1-ME1 axis is reprogrammed to enhance NADPH production; silencing GOT1 or suppressing ME1 leads to intracellular ROS accumulation, redox imbalance, and loss of proliferation." (PMID 41142618, 2025).
preeclampsia (3 papers, 2020 to 2024). Preeclampsia is a hypertensive disorder of pregnancy that is characterized by new-onset hypertension with proteinuria presenting after 20 weeks of gestation, and depending on mild or severe forms may initially present with severe headache, visual disturbances, and hyperreflexia. "GOT1-related pathway was associated with abnormal ferroptosis in preeclampsia." (PMID 39605941, 2024). "In summary, the P15R variant in the GOT1 gene identified in the present study may lead to preeclampsia by causing abnormal synthesis of glutamate or hydrogen sulfide." (PMID 32143588, 2020). "Thus, the decrease in L-glutamate release due to the P15R variant in the GOT1 gene could be related to the occurrence of preeclampsia in this patient." (PMID 32143588, 2020).
cervical cancer (2 papers, 2021). A primary or metastatic malignant neoplasm involving the cervix. "Besides that, low transcript levels retrieved from TCGA primary tumors for three of the 11 ‘hub proteins’ (ALDH7A1, GOT1, MTHFD1) were associated with poor overall survival in renal and cervical cancer (p-value ≤ 0.05; Human Protein Atlas platform)." (PMID 34186243, 2021). "However, in cervical cancer, upregulation of GOT1 mRNA is a protective factor, indicating a better prognosis." (PMID 34590603, 2021).
dyslipidemia (2 papers, 2014 to 2016). "It is quite clear that GOT1 is involved in the regulation of fatty acid levels, and this would support the hypothesis of a possible involvement of GOT1 in the association between metabolic syndrome and leiomyoma growth." (PMID 27070597, 2016).
ischemic stroke (2 papers, 2023 to 2024). A stroke disorder caused by obstruction of blood flow to the brain, due to thrombotic (local blood clot formation) or embolic (due to a blood clot or other material traveling from another site) event. "Previously, elevated serum glutamate and GOT1 levels were reported to be correlated with poor outcomes in ischemic stroke patients." (PMID 37002262, 2023).
multiple myeloma (2 papers, 2022 to 2024). "In multiple myeloma, GOT1 expression was inhibited by shikonin, enhancing ferroptosis in multiple myeloma cells by promoting the release of autophagic labile iron." (PMID 39777342, 2024). "For example, the expression of GOT1 was suppressed by hypoxia-inducible factor-1α (HIF-1α) in VHL-deficient human renal carcinoma, and by electron transport chain (ETC) in human Raji lymphoma and KMS-26 multiple myeloma, leading to impaired proliferation of cancer cells." (PMID 39777342, 2024).
neuroblastoma (2 papers, 2021 to 2023). Neuroblastoma (NB) is the most common solid, extracranial childhood tumor. "A number of genes involved in mitochondrial function and responsive to PGC-1α overexpression in human neuroblastoma cells are reduced, including ATP5A1, glutamic-oxaloacetic transaminase 1 (GOT1;), IDH3A, and malate dehydrogenase 1 (MDH1;)." (PMID 33572179, 2021).
Stroke (2 papers, 2023). Sudden impairment of blood flow to a part of the brain due to occlusion or rupture of an artery to the brain. "Although a few studies have suggested a possible neuroprotective effect of brain GOT1 in various neuro-pathologies, including stroke, the role of brain GOT1 activity in SAH has yet to be studied." (PMID 37002262, 2023). "We and our colleagues previously reported a neuroprotective effect of reducing blood glutamate levels by the administration of recombinant GOT1 and oxaloacetate in SAH, spinal cord injury, stroke, and Paraoxon intoxication animal models." (PMID 37002262, 2023).
viral infection (2 papers, 2023 to 2025). "Here we show that chronic viral infections induce CD8+ T cell expression of GOT1, a central enzyme in the malate shuttle." (PMID 37813964, 2023). "We discovered that CD8+ Tex cells expressed high levels of GOT1 during chronic viral infection." (PMID 37813964, 2023). "In cases of virus infection, Siniperca chuatsi rhabdovirus (SCRV) and infectious spleen and kidney necrosis virus (ISKNV) have been shown to upregulate the expression of GOT1, GOT2, MDH1 and MDH2, thereby supplying substrates for asparagine biosynthesis and promoting virus replication." (PMID 41299514, 2025). "Likewise, upregulation of MAS components, particularly the aminotransferases GOT1 and GOT2, has been observed during viral infections." (PMID 41299514, 2025).
allergic asthma (1 paper, 2025). A asthma with a basis in a pathological type I hypersensitivity reaction. "We also found phenylpyruvate in the memory Teff and Treg cells, as well as upregulated expression of GOT1 and GOT2 in Th2 cells of allergic asthma patients, suggesting that they might be involved in faster turnover of Phe driving pathogenic Th2 cell activity." (PMID 41308641, 2025). "In addition, we noted that GOT1 and GOT2 were significantly upregulated in allergic asthma patients in Th2 cells." (PMID 41308641, 2025).
Alzheimer disease (1 paper, 2020). A progressive, neurodegenerative disease characterized by loss of function and death of nerve cells in several areas of the brain leading to loss of cognitive function such as memory and language. "In addition, many genes closely related to neurological diseases, such as Got1, ApoE, Gm2a, have been found to interact with TET1 in OPCs; and Cst3 is associated with dementia in Lewy body disease and Alzheimer's Disease." (PMID 32974003, 2020).
astrocytomas (1 paper, 2021). "The expression levels of GLUD1, GOT1, GOT2, and GPT2 were differentially expressed in astrocytomas compared to NN (p < 0.0001 Kruskal–Wallis test for GLUD1, GOT1, and GPT2 and p < 0.002 for GOT2)." (PMID 33910646, 2021). "Expression analysis of transcript coding for the key enzymes involved in glutaminolysis, GLSiso1, GLSiso2, GLS2, GLUD1, GOT1, GOT2, and GPT2 was performed in our series of astrocytomas of different malignant grades and NN brain samples." (PMID 33910646, 2021).
breast adenocarcinoma (1 paper, 2016). "Oxamate inhibits GOT1, disrupting the growth of breast adenocarcinomas." (PMID 27070597, 2016). "Glycolysis is increased in breast adenocarcinoma, and GOT1 is a key glycolytic enzyme." (PMID 27070597, 2016).
carcinoid (1 paper, 2005). "In the present study, we analysed the effect of treatment with [177Lu-DOTA0-Tyr3]-octreotate of the human midgut carcinoid GOT1 xenografted to nude mice." (PMID 16251870, 2005).
carcinoid tumours (1 paper, 2005). "The exceptional results obtained in GOT1 xenografts may thus indicate a possibility for more successful treatment of patients with metastatic carcinoid tumours than hitherto achieved in clinical series." (PMID 16251870, 2005).
cerebral infarct (1 paper, 2023). "Medioresinol, a PGC-1α activator, reduces cerebral infarct volume and blood‒brain barrier permeability through the PPARα/GOT1 axis, inhibits endothelial cell pyroptosis, and promotes long-term neurobehavioral recovery." (PMID 38102696, 2023).
endometrial carcinoma (1 paper, 2020). A malignant tumor arising from the epithelium that lines the cavity of the uterine body. "According to available RNA-seq data, high expression levels of cCAT-encoding GOT1 and mCAT-encoding GOT2 are detected in several cancer types, including liver, colorectal, prostate, head and neck, cervical, stomach, endometrial carcinomas, and melanoma." (PMID 32882966, 2020).
esophageal squamous cell carcinoma (1 paper, 2024). Esophageal squamous cell carcinoma (ESCC) is a type of esophageal carcinoma (EC) that can affect any part of the esophagus, but is usually located in the upper or middle third. "Non-coding RNA circGOT1 sponged miR-606 to promote GOT1, which induced glycolytic metabolism of esophageal squamous cell cancer cells, promoting cell proliferation." (PMID 39777342, 2024). "CircGOT1 promoted the expression of GOT1 via sponging miR-606 to exert carcinogenesis including promoting tumor growth, migration, and glycolytic metabolism of esophageal squamous cell cancer cells." (PMID 39777342, 2024).
gastric cancer (1 paper, 2020). A primary or metastatic malignant neoplasm involving the stomach. "Our study showed that GOT1 and GOT2 were decreased in trastuzumab resistant gastric cancer cells with GATA6 knockout, suggesting that GATA6 maintains basal expression of GOT1 and GOT2." (PMID 33173435, 2020).
heart failure (1 paper, 2024). Inability of the heart to pump blood at an adequate rate to meet tissue metabolic requirements. "Cytoplasmic aspartate aminotransferase (Got1) is associated with heart failure and has been described as a potential marker for cancer." (PMID 39457679, 2024).
leiomyoma (1 paper, 2016). A well-circumscribed benign smooth muscle neoplasm characterized by the presence of spindle cells with cigar-shaped nuclei, interlacing fascicles, and a whorled pattern. "In addition, PTRF co-expresses with KRT1, CCT5 co-expresses with MHI1; GOT1 co-expresses with MHI1; and MHI1 co-expresses with LDHB; indicating not only an interaction between LDHB, GOT1 and MDH1, but also a possible association between them and the leiomyoma." (PMID 27070597, 2016).
lymphoma (1 paper, 2024). A malignant (clonal) proliferation of B- lymphocytes or T- lymphocytes which involves the lymph nodes, bone marrow and/or extranodal sites. "Among all genes, lactate dehydrogenase genes (LDHA and LDHB) were observed to be the most highly expressed (among the entire transcriptome), followed by transaminase genes (GOT1, GOT2, GPT, and GPT2) with log2 median expression > 10, both in lymphoma patients and cell lines." (PMID 39518046, 2024).
middle cerebral artery infarction (1 paper, 2023). Necrosis occurring in the middle cerebral artery distribution system which brings blood to the entire lateral aspects of each cerebral hemisphere. "Moreover, CASP3, CASP6, as well as GOT1 and IL1RN, have been implicated in vascular dementia, middle cerebral artery infarction and transient cerebral ischemia (FDR = 0.041)." (PMID 38107644, 2023).
mild cognitive impairment (1 paper, 2025). "Endo-lysosomal proteins (e.g., HEXB, TPP1, SIAE) increased early in abundance alongside neurodegeneration-related proteins, and were followed by increases in metabolic proteins such as ALDOA, MDH1, and GOT1 at the mild cognitive impairment (MCI) stage." (PMID 40329321, 2025).
myocardial ischemia (1 paper, 2022). A disorder of cardiac function caused by insufficient blood flow to the muscle tissue of the heart. "Proteins, such as LDHB, PGAM2, GOT1, PKM2 or AK1, whose expressions are decreased in hCOX-2 Tg animals, have been identified as potential biomarkers during myocardial ischemia." (PMID 36362254, 2022).
pancreatic NETs (1 paper, 2025). "It is essential to establish RBE for relevant tumor cell lines such as GOT1, particularly given the potential local control benefits of adjuvant EBRT in patients with pancreatic NETs." (PMID 40404397, 2025).
Prostate tumors (1 paper, 2020). "Elevated levels of GOT1 have also been observed in malignant high Gleason score Prostate tumors when compared to controls." (PMID 32322560, 2020).
renal carcinoma (1 paper, 2022). A carcinoma arising from the epithelium of the renal parenchyma or the renal pelvis. "At the molecular level, we found that SLC2A1, LDHA, GOT1, and GOT2 were regulated by HGD and GSTZ1 to alter the glucose uptake and energy metabolism of renal cancer cells." (PMID 35562974, 2022).
renal clear cell carcinoma (1 paper, 2021). "Expressions of CRAs, CD44, DPP4, GOT1 and HMGCR were significantly increased in renal clear cell carcinoma compared with those in normal kidney tissue." (PMID 33996565, 2021).
retinal degeneration (1 paper, 2023). Degeneration of the retina. "Ex vivo studies have demonstrated that the retina relies on aspartate aminotransferases for amino acid metabolism, and GOT1 has been shown to be a biomarker of early retinal degeneration in retinitis pigmentosa, suggesting a possible target for therapeutic approaches." (PMID 38725581, 2023).
retinal detachment (1 paper, 2026). An eye emergency condition which may lead to blindness if left untreated. "Interestingly, GOT2, but not GOT1, is decreased in multiple models of PR degeneration, including retinal detachment (RD) where the NAD+/NADH ratio favors a reductive state." (PMID 41993491, 2026).
sarcopenia (1 paper, 2020). Progressive decline in muscle mass due to aging which results in decreased functional capacity of muscles. "A new prediction model with high accuracy can be developed based on four identified molecular markers (SEPP1, SV2A, GOT1, and GFOD1) and used by clinicians to predict the risk of sarcopenia." (PMID 33221762, 2020). "LASSO regression model was used to select 4 key differentially expressed (SEPP1, GFOD1, GOT1, and SV2A) mRNAs (DEMs) predictors of sarcopenia risk and the lasso parameter (lambda.min) was 0.01038519." (PMID 33221762, 2020). "A new model for predicting sarcopenia based on four molecular markers SEPP1, SV2A, GOT1, and GFOD1 was developed." (PMID 33221762, 2020). "SEPP1 mRNAs were upregulated and GFOD1, GOT1, and SV2A mRNAs were downregulated in the sarcopenia group." (PMID 33221762, 2020). "Combined with the nomogram prediction model results, SEPP1, GFOD1, GOT1, and SV2A may be key modulators of sarcopenia." (PMID 33221762, 2020). "Besides, this study is the first to predict the occurrence of sarcopenia based on four molecular markers (SEPP1, SV2A, GOT1, and GFOD1)." (PMID 33221762, 2020). "Interestingly, the results of LASSO regression in this study reveals that the four characteristic factors (SEPP1, GOT1, GOFD1, and SV2A) have an important role in the prediction of sarcopenia." (PMID 33221762, 2020). "SEPP1 and DLEU2 expression levels were higher in patients with sarcopenia than in patients without sarcopenia, while the expression levels of GFOD1, GOT1, SV2A, and miR-181a were significantly lower in patients with sarcopenia than in patients without sarcopenia." (PMID 33221762, 2020).